NFE2L2 (NFE2 like bZIP transcription factor 2)
Diseases named in the same sentence as NFE2L2 in open-access papers (continued):
Sharing a sentence is not in itself a finding about the gene and the disease.
cardiac hypertrophy (7 papers, 2019 to 2026). "Studies in Nfe2l2-KO mice demonstrated that Nfe2l2 gene deficiency leads to LV diastolic dysfunction with mild cardiac hypertrophy but preserved systolic function and heart failure following myocardial infarction." (PMID 35204118, 2022). "Additionally, LV diastolic dysfunction in Nfe2l2-KO mice is associated with cardiac hypertrophy and the downregulation of the sarcoplasmic reticulum Ca(2+)-ATPase (SERCA2a) in the myocardium." (PMID 35204118, 2022). "Nfe2l2-KO mice develop cardiac hypertrophy, LV diastolic dysfunction, and impaired calcium homeostasis." (PMID 35204118, 2022).
kidney damage (7 papers, 2016 to 2025). "We conducted this study to investigate NFE2L2 SNPs for possible associations with either T2DM or diabetic complications (including diabetic foot, nephropathy, retinopathy, microangiopathy and peripheral neuropathy) in a cohort of Chinese volunteers of Han descent." (PMID 27374075, 2016). "In nephropathy, activation of NFE2L2 reduces oxidative damage and negatively regulates TGFB1 & extracellular matrix production." (PMID 28761062, 2017).
ulcerative colitis (7 papers, 2012 to 2025). An inflammatory bowel disease involving the mucosal surface of the large intestine and rectum. "The results of a cycle of studies performed by Japanese scientists suggest that NFE2L2 allelic variants are associated with tumorigenesis in the gastrointestinal tract and risk of inflamed bowel syndrome caused by ulcerative colitis." (PMID 36980990, 2023). "An NFE2L2/NRF2 gene promoter polymorphism is associated with ulcerative colitis in a Japanese population, implying that GPX2 may modify IBD." (PMID 22970191, 2012).
acute lung injury (6 papers, 2016 to 2025). A condition of lung damage that is characterized by bilateral pulmonary infiltrates (pulmonary edema) rich in neutrophils, and in the absence of clinical heart failure. "Nuclear factor erythroid-derived 2-like 2 (Nfe2l2, also known as Nrf2), a nuclear transcription factor, is reported to play protective roles in acute lung injury (ALI) and inflammation, and increasing evidence indicates that the protective effects of Nrf2 are closely related to autophagy." (PMID 36497185, 2022).
brain injury (6 papers, 2020 to 2025). Acute and chronic (see also brain INJURIES, CHRONIC) injuries to the brain, including the cerebral hemispheres, CEREBELLUM, and brain STEM. "In ischemic brain injury, LFHP-1c inhibits microglial activation, attenuates endothelial cell apoptosis, and reduces neuroinflammation through 5′-adenosine monophosphate-activated protein kinase (AMPK) and nuclear factor erythroid 2-like 2 (NRF2, NFE2L2) activation." (PMID 40361499, 2025).
epilepsy (6 papers, 2021 to 2025). A brain disorder characterized by episodes of abnormally increased neuronal discharge resulting in transient episodes of sensory or motor neurological dysfunction, or psychic dysfunction. "In this research, we identified six characteristic genes associated with ferroptosis in epilepsy: NFE2L2, PTGS2, IL6, JUN, HMOX1, and TLR4." (PMID 37946105, 2023). "We have identified six feature genes (IL6, PTGS2, HMOX1, NFE2L2, TLR4, and JUN) strongly associated with ferroptosis in epilepsy, suggesting their potential as biomarkers for the diagnosis of temporal lobe epilepsy." (PMID 37946105, 2023). "Increased expression of NFE2L2 gene has been shown to protect the cells against epilepsy by increasing antioxidant properties in neuronal cells." (PMID 34588521, 2021). "Based on the present results, ferroptosis-related hub genes NFE2L2, PTGS2, IL6, JUN, HMOX1, and TLR4 have good diagnostic value for epilepsy and may be potential early biological diagnostic targets." (PMID 37946105, 2023). "Interestingly, downregulation of EGLN1, ELAVL4, NFE2L2 KCNK18 genes was only detected in epilepsy-related (CvsE) gene list." (PMID 34588521, 2021). "There are 2 genes (NFE2L2 and EGLN1) related to these features in the CvsE group and there are studies in the literature suggesting that these genes are related to epilepsy." (PMID 34588521, 2021). "Interestingly, we observed that when compared to the normal controls, the expression of some identified genes was only significantly altered either in Epilepsy (EGLN1, ELAVL4, and NFE2l2) or Hemorrhage (USP22, EYA1, SIX1, OAS3, SRMS) groups." (PMID 34588521, 2021).
oral cancer (6 papers, 2017 to 2022). "Pomegranate extract also downregulates NFE2L2, TXN, CAT, SOD1, and HMOX1 gene expressions in oral cancer cells and induces oxidative stress." (PMID 36139851, 2022). "In response to oxidative stresses, the mRNA for antioxidant signaling, such as nuclear factor erythroid 2-like 2 (NFE2L2), catalase (CAT), heme oxygenase 1 (HMOX1), and thioredoxin (TXN), are overexpressed in oral cancer cells." (PMID 34575651, 2021). "In the present study, EANT generates oxidative stress, which is accompanied by mRNA overexpression for antioxidant genes (NFE2L2, CAT, HMOX1, and TXN) in oral cancer cells." (PMID 34575651, 2021). "Similar to the present study, the mRNA expressions for several antioxidant genes (NFE2L2, GCLC, TXN, CAT, SOD1, HMOX1, and NQO1) were downregulated at 24 h POMx for three oral cancer cell lines." (PMID 34356350, 2021). "Accordingly, the antioxidant signaling gene expression for mRNA, including NFE2L2, GCLC, TXN, CAT, SOD1, HMOX1, and NQO1, was examined for POMx-incubated oral cancer cells." (PMID 34356350, 2021). "In the current study, antioxidant gene expressions (NFE2L2, SOD1, TXN, GSR, CAT, and GPX1) in oral cancer Ca9-22 and CAL 27 cells were highly downregulated by UVC/sinularin combined treatments compared to the separate treatments." (PMID 34070049, 2021). "Accordingly, the gene expressions of antioxidant genes such as NFE2L2, SOD1, TXN, GSR, CAT, and GPX1 were evaluated by qRT-PCR following UVC and/or sinularin treatments in oral cancer cells (Ca9-22 and CAL 27)." (PMID 34070049, 2021). "Consistently, we found that low concentrations of WFA induced mRNA expressions of NFE2L2, HMOX1, and NQO1 genes, which may lead to inhibitory migration of oral cancer cells." (PMID 32429564, 2020).
osteoarthritis (6 papers, 2020 to 2025). A noninflammatory degenerative joint disease occurring chiefly in older persons, characterized by degeneration of the articular cartilage, hypertrophy of bone at the margins and changes in the synovial membrane. "Preclinical research indicates that HDAC inhibitors, such as trichostatin A, enhance the acetylation of the NFE2L2 promoter in murine models of osteoarthritis, thereby restoring Nrf2-driven antioxidant defenses." (PMID 40868167, 2025).
psoriasis (6 papers, 2020 to 2025). An autoimmune condition characterized by red, well-delineated plaques with silvery scales that are usually on the extensor surfaces and scalp. "Furthermore, mice with knockout of the ArpC4 subunit in keratinocytes [Arpc4f/f::K14-Cre(neo)] displayed skin abnormalities at birth that resulted in a psoriasis-like disease characterised by hyperactivation of the transcription factor Nrf2 (Nfe2l2)." (PMID 33028610, 2020). "Psoriasis skin-derived S.B cells expressed GPX4, FTL, and FTH1 at high levels, whereas control skin-derived S.G & S.S cells expressed high levels of GPX4, FTH1, NR4A1, NFE2L2, and MT1G." (PMID 35962439, 2022).
thyroid cancer (6 papers, 2019 to 2025). "We proceeded to analyze mutations in the SOSTM1, KEAP1, and NFE2L2 genes in patients with thyroid cancer." (PMID 41394539, 2025). "Notably, qRT‐PCR analysis showed that IDET considerably upregulated the expression of KEAP1 and NFE2L2 mRNAs in thyroid cancer cells, where Nrf2 is encoded by NFE2L2." (PMID 41394539, 2025). "In thyroid cancer cells, the expression of miR-17-5p was reported to be a potential biomarker, regulating NFE2L2 expression." (PMID 35806488, 2022). "Deregulation of VEGFA (Vascular Endothelial Growth Factor A) and NFE2L2 (Nuclear Factor (Erythroid-derived 2)-Like 2), involved in angiogenesis and oxidative stress, can lead to thyroid cancer progression." (PMID 32824922, 2020). "These contrasting results may reflect the participation of other active pathways in thyroid cancer that could influence NFE2L2 expression." (PMID 32824922, 2020). "Occasional NFE2L2 and KEAP1 mutations were recently identified as part of whole-exome sequencing analysis of patient cohorts with Hürthle-cell (oncocytic) thyroid carcinoma (HCC), a type of differentiated thyroid carcinoma characterized by cells with abundant but dysfunctional mitochondria." (PMID 31428048, 2019). "The TCGA (The Cancer Genome Atlas Program) thyroid cancer dataset showed that VEGFA and NFE2L2 were highly expressed in normal tissue (n = 59) when compared with the primary tumor (n = 505)." (PMID 32824922, 2020).
diabetic neuropathy (5 papers, 2022 to 2025). A chronic, pathological complication associated with diabetes mellitus, where nerve damages are incurred due to diabetic microvascular injury involving small blood vessels that supply these nerves, resulting in peripheral and/or autonomic nerve dysfunction. "Rutin administered to mice reduced oxidative stress to mitigate diabetic neuropathy by means of HMOX1 and NFE2L2." (PMID 40429928, 2025).
endometrial cancer (5 papers, 2014 to 2025). Primary or metastatic malignant neoplasm involving the endometrium (mucous membrane that lines the endometrial cavity). "Mutations in the NFE2L2 (NRF2) gene were found in around 2% of studies and the highest percentage of mutations was found in endometrial carcinoma (12%) and lung adenocarcinoma (11%)." (PMID 39941813, 2025). "As an example, we identified hotspot regions in the NFE2L2 gene that are potentially functionally relevant in endometrial cancer, but would be missed using other analyses." (PMID 25435088, 2014).
osteosarcoma (5 papers, 2016 to 2024). A usually aggressive malignant bone-forming mesenchymal neoplasm, predominantly affecting adolescents and young adults. "Decreased levels would be expected to increase tumor cell susceptibility to apoptosis, yet NFE2L2 deficiency may increase the risk of pulmonary metastasis although the significance of decreased expression of the gene in osteosarcoma is not well understood." (PMID 27812189, 2016).
preeclampsia (5 papers, 2015 to 2024). Preeclampsia is a hypertensive disorder of pregnancy that is characterized by new-onset hypertension with proteinuria presenting after 20 weeks of gestation, and depending on mild or severe forms may initially present with severe headache, visual disturbances, and hyperreflexia. "CREBBP interacts with several proteins well known to be associated with preeclampsia, such as NFE2L2, LEP and VEGF/FLT1, but also with proteins not-yet related to preeclampsia." (PMID 26171964, 2015).
Arthritis (4 papers, 2014 to 2024). Inflammation of a joint. "Finally, transcription factor motif enrichment analysis revealed transcription factors such as Rela, Relb, Junb, Nfe2l2, and Bach1 that could regulate the expression of Mir221/222 in arthritis." (PMID 39235454, 2024).
diabetic foot ulcers (4 papers, 2016 to 2025). "Clinical analyses reveal HDAC4 overexpression in patients with diabetic foot ulcers inversely correlates with NFE2L2 expression, suggesting that deacetylation may suppress NFE2L2 activity." (PMID 40868167, 2025).
emphysema (4 papers, 2009 to 2024). "Previous in vivo reports show that NFE2L2 deletion leads to severe emphysema and oxidative stress, upon prolonged CSE81,82." (PMID 36333510, 2022). "Moreover, murine models have shown that the Nfe2l2 depletion in vivo results in elastase- and cigarette smoke-induced emphysema development." (PMID 19671143, 2009).
hepatoblastoma (4 papers, 2022 to 2025). Hepatoblastoma (HB) is a malignant hepatic tumor and is the most common pediatric liver cancer. "Following DNA sequencing studies further validated that mutations in the WNT–β-catenin pathway genes are the main genetic events in hepatoblastoma and also identified other rare genetic mutations in NFE2L2 and TERT genes." (PMID 40684183, 2025). "Additionally, mutations in the NFE2L2 gene, which has been linked to resistance against cisplatin, were identified in 5% of hepatoblastomas." (PMID 38390281, 2024). "The hepatoblastoma driver genes CTNNB1 and NFE2L2, along with liver-specific transcription factors HNF1A and HNF4A, were also found to be essential for cell survival." (PMID 40684183, 2025). "Notedly, any two subtypes of the catenin-yaps127a-l30p/R34P mutants of NFE2L2 in hepatoblastoma of children are tumorigenic without relying on the activity of KEAP1, providing direct proof of NFE2L2 being an oncoprotein." (PMID 37794491, 2023).
injury (4 papers, 2021 to 2023). Damage inflicted on the body as the direct or indirect result of an external force, with or without disruption of structural continuity. "The flavanol (-)-epicatechin has been demonstrated to provide cerebroprotection after a traumatic brain injury via NFE2L2-dependent and -independent pathways." (PMID 36771351, 2023). "By analysis of the published data from the ischemic AKI model developed with unilateral renal ischemia–reperfusion injury (GSE192883), the relative gene expression of Nfe2l2, Plk2, and Cdkn1a was upregulated." (PMID 35842499, 2023).
lung disease (4 papers, 2018 to 2024). "In this study, we analyzed the participation of the polymorphisms of NFE2L2 and KEAP1 genes in the mechanisms of damage in lung disease patients with SARS-CoV-2 infection." (PMID 36613859, 2022). "In this study, therefore, we sought to describe the participation of the single nucleotide polymorphisms (SNPs) of the NFE2L2 (rs2364723) localized in the intronic region and KEP1 (rs967688 and rs34197572) genes localized in the 3’UTR region in lung disease in patients with SARS-CoV-2 infection." (PMID 36613859, 2022).
Parkinson’s (4 papers, 2016 to 2022). "In our study, in PD patients with NFE2L2 variants (117E and 141H), we observed the effects of the NFE2L2 variants on its downstream gene expression including GSTM1 and SOD1, a major antioxidant enzyme in Parkinsonism." (PMID 26887053, 2016).
type 1 diabetes (4 papers, 2022 to 2024). "We assessed the association between rs2364723 of NFE2L2 and oxidative stress in children/adolescents with type 1 diabetes (T1D)." (PMID 36139799, 2022). "Furthermore, we found that ATP7B was associated with antigen processing and presentation, autoimmune thyroid disease, type I diabetes mellitus and intestinal immune network for IgA production, while NFE2L2 was involved in the Toll-like receptor signaling pathway." (PMID 38690269, 2024).
vitiligo (4 papers, 2017 to 2025). Generalized well circumscribed patches of leukoderma that are generally distributed over symmetric body locations and is due to autoimmune destruction of melanocytes. "Moreover, KBL was found to modulate vitiligo via the regulation of activity of multiple series enzymes such as tyrosinase (TYR), oxidoreductase (GSTP1, CAT, MPO, and GSTM1), and controlling signal transducer (NFE2L2)." (PMID 31781265, 2019).
acute pancreatitis (3 papers, 2022 to 2026). An acute inflammatory process that leads to necrosis of the pancreatic parenchyma. "Notably, Sesn2, Kras, Hmox1, and Nfe2l2 exhibited significant expression differences during acute pancreatitis, suggesting they may serve as potential biomarkers for the condition." (PMID 41894401, 2026).
Cirrhosis (3 papers, 2018 to 2023). A chronic disorder of the liver in which liver tissue becomes scarred and is partially replaced by regenerative nodules and fibrotic tissue resulting in loss of liver function. "Specimens from patients diagnosed with cirrhosis caused by ALD were genotyped for three NFE2L2 single nucleotide polymorphisms (SNP) (SNPs: rs35652124, rs4893819, and rs6721961)." (PMID 31340446, 2019). "In conclusion, our findings provide evidence that single nucleotide variations in the promoter region of NFE2L2, specifically the variant –274A of SNP rs35652124, might contribute to the pathogenesis of cirrhosis from ALD." (PMID 31340446, 2019). "Together, these results are consistent with the idea that the polymorphism -274A in the promoter region of NFE2L2 predisposes to ALD while the polymorphism at -178A might be associated with susceptibility to develop cirrhosis from ALD plus other causes as well." (PMID 31340446, 2019).
clear cell renal carcinoma (3 papers, 2014 to 2024). A malignant epithelial neoplasm of the kidney characterized by the presence of lipid-containing clear cells within a vascular network. "Analysis of available survival datasets obtained from GEO and TCGA databases showed that lower expression of Nrf2 (NFE2L2) is associated with a significantly poorer outcome in skin cutaneous melanoma (SKCM) (P = 0.0341) and in kidney clear cell carcinoma (KIRC) (P = 0.0203)." (PMID 24491031, 2014).
diabetic cardiomyopathy (3 papers, 2019 to 2022). Diabetic cardiomyopathy is a disorder of the heart muscle in people with diabetes. "According to some studies, enhancing NFE2L2 activity may be beneficial in diabetic cardiomyopathy, mitochondrial dysfunction, and as an anti-aging agent, but further studies are needed." (PMID 31013989, 2019).
fibrosis (3 papers, 2019 to 2022). the formation of excess fibrous connective tissue in an organ or tissue in a reparative or reactive process. "With respect to this, the overexpression of Nfe2l2 inhibited cardiac fibrosis and dysfunction; meanwhile, Nfe2l2-KO mice develop cardiac fibrosis and dysfunction after transverse aortic constriction surgery." (PMID 35204118, 2022).
infertile (3 papers, 2019 to 2024). "The results revealed an increase in GLS and NFE2L2 expression in the endometrium of patients with EMT; however, a decrease in GLS and NFE2L2 expression was observed in the endometrium of patients with infertility." (PMID 38062233, 2023).
laryngeal carcinoma (3 papers, 2017 to 2022). Carcinoma that arises from the laryngeal epithelium. "In our series, NFE2L2 rs2706110 and rs1303586 less common genotypes were linked with lower risk of developing laryngeal cancer, while in pharyngeal cancer, only rs1303586 was associated." (PMID 30959967, 2019).
prion disease (3 papers, 2008 to 2017). A transmissible disease that is caused by a protein that is able to induce abnormal folding of normal cellular proteins, leading to characteristic spongiform brain changes, which are associated with neuronal loss without an inflammatory response. "In addition, Nfe2l2 is annotated in KEGG as associated with prion disease." (PMID 18769717, 2008).
renal carcinoma (3 papers, 2017 to 2025). A carcinoma arising from the epithelium of the renal parenchyma or the renal pelvis. "A growing amount of evidence suggest that an increased activity of Nrf2 due to NFE2L2 or KEAP1 mutations may play a pivotal role in the pathogenesis of many solid tumors and recently emerged as one of the main pathways implicated in Renal Carcinoma." (PMID 28061437, 2017).
stomach cancer (3 papers, 2020 to 2025). "The expression levels of CXCR4 and NFE2L2 as well as four differentially expressed NRGs (SPP1, CXCL1, MMP9, and TIMP1) were validated in gastric tumor cells and clinical samples." (PMID 38221932, 2024).